DUOX1 (dual oxidase 1)
Diseases named in the same sentence as DUOX1 in open-access papers (continued):
Sharing a sentence is not in itself a finding about the gene and the disease.
asthma (8 papers, 2016 to 2024). "In asthma, the expression of DUOX1 increased, and the underlying mechanism of IL-13-mediated increase in superoxide levels is that autophagy pathway could direct DUOX1 to the apical surface of the airway epithelium." (PMID 32082074, 2019). "DUOX1-induced ROS production has also been shown in various diseases, such as DUOX1 nasal polyposis, allergy and asthma, chronic obstructive pulmonary disease, lung fibrosis and cancer." (PMID 38750444, 2024). "This brings about the activation of pro-oxidant enzymes, such as DUOX1, and increases IL33 production and, ultimately, airway epithelial injury, predisposing PCD lungs toward asthma development." (PMID 39337527, 2024). "In asthma, allergen exposure increases DUOX-1 expression by the nasal epithelium, and neutrophil-derived ROS production by Der f 1 is greater than in controls without asthma." (PMID 29976563, 2018). "Other mechanisms of Duox1 regulation of asthma include enhanced inflammatory mediators including IL-8 or matrix metalloprotease-9 (MMP-9) and increased airway acidification." (PMID 29257052, 2017). "Poor antigen clearance results in pro-oxidant pathway activation and airway epithelial damage and may predispose PCD patients to DUOX1- and IL33-mediated asthma." (PMID 39337527, 2024). "In addition to postulated roles in airway host defense, recent studies have suggested alternative functions of airway epithelial Duox1 in mediating asthma." (PMID 29257052, 2017). "Targeted inhibition of airway Duox1 in mice reversed symptoms of asthma." (PMID 29257052, 2017). "In addition to the role of Duox in asthma, Nox4 was also identified to express along with Duox1 and Duox2 in bronchial biopsy specimens by using microarray." (PMID 29257052, 2017). "NOX4 and DUOX1/2 expression in the epithelium was evident in asthma." (PMID 26836936, 2016). "Indeed, chronic allergic airway diseases such as asthma are characterized by upregulation of airway DUOX1 as a contributing factor to heightened Th2 responses to allergen challenge, and increased mucus hyperplasia and airway remodelling as major features of asthma pathology." (PMID 34829671, 2021). "DUOX1 was increased in asthma independent of inflammatory phenotype, and DUOX2 was only increased in nonneutrophilic asthma." (PMID 26836936, 2016). "Nox4 and Duox1 were both elevated and Duox2 was elevated in nonneutrophilic asthma." (PMID 29257052, 2017). "Levels of 8-oxo-dG and NOX4 were elevated in patients with neutrophilic vs nonneutrophilic asthma, DUOX1 was elevated in both, and DUOX2 was elevated in nonneutrophilic asthma in vivo." (PMID 26836936, 2016). "Gene array analysis revealed the presence of NOX4 and DUOX1 and DUOX2 expression, but not the other NOX family members, in primary basal epithelial cells from ≥ 3 of the six donors with asthma." (PMID 26836936, 2016). "In contrast to DUOX1, which was increased in asthma independent of inflammatory phenotype, and DUOX2, which was only increased in nonneutrophilic asthma, NOX4 expression was upregulated only in the bronchial epithelium from patients with asthma with neutrophilic inflammation in vivo." (PMID 26836936, 2016).
congenital hypothyroidism (8 papers, 2017 to 2023). A thyroid hormone deficiency present from birth. "Whole-exome sequencing in siblings with a known homozygous DUOX2 mutation and unusually marked congenital hypothyroidism (CH) identified the human homozygous DUOX1 mutation, segregating with CH." (PMID 28633507, 2017). "Ultimately, the crucial role of DUOX1 in human thyroid function was demonstrated in patients with congenital hypothyroidism (CH): two heterozygous missense mutations in DUOX1 and DUOXA1 in two patients can cause CH through disrupting the coordination of DUOX1 and DUOXA1 in the generation of H2O2." (PMID 36835420, 2023). "DUOX2/DUOXA2 defects can cause congenital hypothyroidism (CH), but it is unknown whether DUOX1/DUOXA1 mutations can also cause CH." (PMID 31428054, 2019). "In addition, a congenital hypothyroidism might have a digenic cause; digenic DUOX1 and DUOX2 causative variants in cases with congenital hypothyroidism have been reported." (PMID 34200080, 2021). "More recently, the first evidence of a physiologic role for DUOX1 in humans was provided by a report of two siblings with homozygous inactivating mutations in both DUOX1 and DUOX2 associated with congenital hypothyroidism more severe than is typically observed in DUOX2 deficiency alone." (PMID 29026407, 2017). "Indeed, mutations in DUOX1 and DUOX2 have been linked with congenital hypothyroidism." (PMID 30700401, 2019). "Although dual oxidase 1 (DUOX1) is highly homologous to DUOX2, isolated defects of DUOX1 have not been reported to cause congenital hypothyroidism." (PMID 29026407, 2017).
hypothyroidism (8 papers, 2017 to 2022). Abnormally low levels of thyroid hormone. "Additionally, in murine models, only DUOX2 loss of function is associated with hypothyroidism; thus, the role of DUOX1 in thyroid biology remains unclear." (PMID 28633507, 2017). "Genes related to TH biogenesis show a normal response to TSH stimulation in hypothyroidism, including Tpo, Pendrin, Tshr, Nis, Mct8, Duox1, Duox2, Duoxa1, and Duoxa2." (PMID 35326426, 2022). "However, because hypothyroidism due to DUOX2 mutations tends to be relatively mild, it has been suggested that DUOX1 may partly compensate for DUOX2 deficiency." (PMID 29026407, 2017). "Additionally, in murine models, only DUOX2, and not DUOX1, loss of function is associated with hypothyroidism; thus, the role of DUOX1 in thyroid biology remains unclear." (PMID 35588090, 2022).
thyroid tumor (6 papers, 2018 to 2025). A benign or malignant neoplasm affecting the thyroid gland. "Overexpression of DUOX1 in radio-induced thyroid tumors suggests that DUOX1 may contribute to chronic oxidative stress and thus, can promote genomic instability and tumorigenesis." (PMID 31083324, 2019). "In addition, Ameziane-El-Hassani and collaborators recently showed that DUOX1 is upregulated in human thyrocytes and in thyroid tumors after genotoxic stress induced by γ-ray irradiation." (PMID 29849884, 2018). "DUOX1 and NOX4 are involved in the generation of ROS in the context of thyroid tumor development, which opens the way for further investigation into their role in the mechanisms that lead to genetic aberrations." (PMID 40620232, 2025).
breast carcinoma (5 papers, 2018 to 2021). "Low expression of CRNN, CLEC3B and DUOX1 were associated with poor prognosis of breast cancer." (PMID 31443700, 2019). "In conclusion, we demonstrate here that DUOX1 is silenced in breast cancer, which seems to be involved in breast carcinogenesis." (PMID 29849884, 2018). "Previous studies have shown that dual oxidase 1 (DUOX1) is commonly downregulated in lung, liver, and breast cancers, suggesting that it may have a tumor suppressor role." (PMID 35087563, 2021). "Taken together, these data suggest that DUOX1 isinvolved in genotoxic stress response in mammary cells, and its downregulationin breast cancer could be related to chemotherapy response." (PMID 32453337, 2020). "In summary, we demonstrate for the first time that DUOX1 is downregulated in breast cancer." (PMID 29849884, 2018). "Finally, the physiological alterations elicited by the downregulation of DUOX1 seem to modify the cellular responses to doxorubicin, one of the most commonly used chemotherapeutic agent for breast cancer treatment." (PMID 29849884, 2018). "Here, we show that DUOX1 is downregulated in breast cancer and that its expression is crucial to the physiology of mammary epithelial cells, once nontumor cells silenced for DUOX1 show increased proliferation rate and decreased migration, adhesion, and cytokine secretion." (PMID 29849884, 2018). "DUOX1 has been involved in breast cancer, whereas the role of DUOX2 on breast cancer is still unreported." (PMID 35046993, 2021). "Moreover, DUOX1 silencing in lung epithelial and cancer cell lines was associated to epithelial-to-mesenchymal transition, which is linked to metastasis, and transient overexpression of DUOXA1, a maturation factor of DUOX1, in breast cancer cells affected cell-cell adhesion." (PMID 29849884, 2018). "Here, we show that DUOX1 expression is decreased in breast cancer cell lines and also in breast cancers when compared to the nontumor counterpart." (PMID 29849884, 2018). "Recently, we demonstrated that DUOX1, but not DUOX2, is downregulated in breastcancer cell lines and breast cancer tissues." (PMID 32453337, 2020).
liver cancer (5 papers, 2015 to 2021). An epithelial or non-epithelial malignant neoplasm that arises from the liver. "The prognostic value of DUOX1 expression is highlighted in liver cancer with low levels of expression, while normal levels were indicative of disease-free survival." (PMID 31443700, 2019). "DUOX1 is frequently downregulated in lung and liver cancers, suggesting a tumor suppressor role for this enzyme." (PMID 29849884, 2018). "Previous evidence has shown that DUOX1 is frequently downregulated in lung and liver cancers." (PMID 35087751, 2021). "Interestingly, while other NOX enzymes are upregulated in cancer cells, explaining the higher amount of ROS generated by them in comparison to their normal counterparts, previous studies have shown a decreased DUOX1 expression in lung and liver cancers." (PMID 29849884, 2018). "Previous studies have shown a decreased DUOX1 expression in lung and liver cancers." (PMID 29849884, 2018). "The group with DUOX1, GLS2 and FBP1 low expression may have 2.562, 2.540 and 3.529 times risk of liver cancer relapse compared with these genes high expression group." (PMID 27079415, 2016). "What’s more, the scoring system including DUOX1, GLS2 and FBP1 acted as predictive model firstly used in our study to predict HCC patients’ survival and this predictive model can be a potential prognostic tool for liver cancer patients." (PMID 27079415, 2016). "In addition, lincRNA-p21 also up-regulated the expression of dual oxidase 1 (DUOX1), which is the main source of ROS, is significantly decreased in HCC and liver cancer cell lines compared to immortalized normal cell lines and adjacent non-tumor tissues." (PMID 26305675, 2015).
viral infections (5 papers, 2019 to 2023). "Age-related DUOX1 downregulation would also be expected to lead to impaired DUOX1-mediated antiviral responses, which may be relevant for the increased susceptibility of ageing individuals to viral infections such as influenza, and possibly also SARS-CoV-2." (PMID 34829671, 2021). "Moreover, in light of recent work indicating a role for DUOX1 in antiviral innate immunity, decreased DUOX1 in the lung of COPD patients may also promote susceptibility to viral infection and may thereby enhance exacerbations." (PMID 34829671, 2021). "Furthermore, several viral infections, including hepatitis B virus (HBV) and HIV, are involved in modulating Ca2+ concentrations, which activates NOX5, DUOX1, and DUOX2." (PMID 37505861, 2023). "Although SCN3A has previously not been described in the context of virus infections, DUOX1 appears to promote the innate immune defense to pathogens via the production of reactive oxygen species." (PMID 33585804, 2021).
cervical cancer (4 papers, 2019 to 2024). A primary or metastatic malignant neoplasm involving the cervix. "This indicates that DUOX1 expression is highly associated with the innate immune cell response in cervical cancer." (PMID 31706280, 2019). "Moreover, high DUOX1 mRNA levels were significantly associated with both favorable overall survival and disease-free survival in cervical cancer patients." (PMID 31706280, 2019). "Moreover, in our study, high expression levels of DUOX1 mRNA were significantly associated with favorable overall survival as well as disease-free survival in cervical cancer patients." (PMID 31706280, 2019). "DUOX1 and NOX2 expression are associated with mucosal immunity activated in cervical squamous cell carcinoma and predicts a favorable prognosis in cervical cancer patients." (PMID 31706280, 2019). "It is discovered that the IHC staining of DUOX1 was increased in secretary cells of uterine cervical glands in cervical cancer tissues." (PMID 31706280, 2019). "DUOX1 was strongly correlated with the ratios of CD8+ T cells, DCs, and NK cells, indicating that its expression was highly associated with the innate immune cell response in cervical cancer." (PMID 37187896, 2023). "However, DUOX1 is overexpressed in patients with cervical cancers." (PMID 37187896, 2023). "Furthermore, DUOX1 expression in innate lymphocytes suggests that DUOX1 has a broad host defense function, resulting in prolonged survival prognosis for patients with cervical cancer." (PMID 37187896, 2023). "This study has extended our knowledge of the roles of DUOX1 and NOX2 in cervical cancer and shed light on its potential clinical use in cervical cancer patients." (PMID 31706280, 2019). "Our results suggest that DUOX1 and NOX2 mediate the IFN-based immune defense against HPV infection, and thereby affect the outcomes of cervical cancer patients." (PMID 31706280, 2019). "Based on GSEA and CIBERSORT analysis, it is suggested that DUOX1 and NOX2 have differential effects on the immune cell-mediated response in cervical cancer patients." (PMID 31706280, 2019). "In cervical cancer patients with HPV infection, DUOX1 and DUOX2 mRNA levels were significantly increased as compared to patients without HPV infection." (PMID 31706280, 2019). "Specifically, we discovered that DUOX1 and NOX2 staining in uterine cervical glands and intraepithelial infiltrating cells in cervical cancer tissues." (PMID 31706280, 2019). "The effects of DUOX1 and NOX2 on survival in cervical cancer patients depend commonly on IFN-alpha and IFN-gamma, and differential pathways of DUOX1 and NOX2 were identified." (PMID 31706280, 2019). "We investigated IHC staining of DUOX1 and NOX2 in cervical cancer tissues based on data from the Human Protein Atlas." (PMID 31706280, 2019). "In this study, the increased mRNA levels of DUOX1, DUOX2, and NOX2 in cervical cancer were identified in TCGA and GEO databases." (PMID 31706280, 2019). "DUOX1, DUOX2, and NOX2 protein expression were also identified in our clinical cervical cancer samples." (PMID 31706280, 2019). "DUOX1 and DUOX2 were also the most abundant NOX transcripts in cervical cancer patients, whereas NOX3 was the least abundant and was undetectable in normal control subjects." (PMID 31706280, 2019). "Dual Oxidase1 (DUOX1) and Dual Oxidase 2 (DUOX2) mRNA levels were upregulated 57.9- and 67.5-fold, respectively, in cervical cancer patients." (PMID 31706280, 2019). "To investigate the immune cell types regulated by DUOX1 and NOX2 mRNA expression in cervical cancer tissues more specifically, we utilized CIBERSORT analysis." (PMID 31706280, 2019). "DUOX1 and NOX2 were reported to exert favorable effects in cervical cancer patients." (PMID 38396964, 2024). "In addition, the expression of four genes, including JUN, TSC22D3, DUOX1, and HELLS, in cervical cancer tissues was verified by qRT-PCR." (PMID 37187896, 2023).
cervical cancer (continued). "We conducted GSEA to verify the effects of DUOX1 and NOX2 on survival in cervical cancer patients." (PMID 31706280, 2019). "Furthermore, the IHC staining of DUOX1 and NOX2 protein was examined in cervical cancer based on data from the Human Protein Atlas." (PMID 31706280, 2019). "Moreover, we analyzed the protein expression of NOX2, DUOX1, and DUOX2 using clinical tissue samples from cervical cancer patients." (PMID 31706280, 2019). "The approach of inducing a DUOX1 and NOX2-mediated immune response in uterine cervical mucosa is clinically expected to reinforce immune response to HPV infection and thus increase the survival of cervical cancer patients." (PMID 31706280, 2019).
emphysema (4 papers, 2018 to 2023). "Neutrophilic inflammation has been implicated in COPD pathology and in elastase-induced emphysema, and previous studies of allergic airways disease have linked DUOX1 to production of neutrophil chemokines (CXCL1) and neutrophil recruitment." (PMID 33301419, 2021). "The GOLD IV patients included in this study underwent lung volume reduction surgery (LVRS) because of severe emphysema, suggesting that DUOX1 downregulation may be associated with emphysema." (PMID 33301419, 2021). "Duox1 deficiency enhanced elastase-induced emphysema in mice." (PMID 33301419, 2021). "Moreover, we provide evidence that DUOX1 deficiency leads to enhanced features of small airway remodeling and emphysema in experimental mouse models of COPD, suggesting that DUOX1 downregulation in COPD may actively contribute to disease pathogenesis." (PMID 33301419, 2021). "Overall, these results imply that the gradual loss of DUOX1 in the small airways of patients with COPD is associated with impaired lung function, emphysema, and airway remodeling in these patients." (PMID 33301419, 2021). "These latter studies also indicated a critical role for DUOX1 in production of IL-13 during allergic inflammation, but Il13 induction in the context of PPE-induced emphysema was unaltered in Duox1-deficient mice." (PMID 33301419, 2021). "The present study aimed to address the importance of DUOX1 downregulation in small airway remodeling as well as emphysema development in COPD." (PMID 33301419, 2021). "Our findings of PPE-induced emphysema suggested that lung tissue Areg mRNA tended to be suppressed in PPE-exposed Duox1–/– mice compared controls, but PPE-induced increases in lung tissue Areg protein levels were similar both WT and Duox1–/– mice." (PMID 33301419, 2021). "Small airway DUOX1 levels were decreased in advanced COPD and correlated with loss of lung function and markers of emphysema and remodeling." (PMID 33301419, 2021). "In conclusion, 2 × 106 BMMCs showed potent anti-inflammatory, antiapoptotic, antioxidant and restorative effects in papain-triggered pulmonary emphysema, possibly by blocking DUOX1 and reducing DUOX2." (PMID 29515461, 2018). "To address a potential causal effect of DUOX1 down-regulation in COPD development or progression, we assessed the impact of DUOX1 deletion in a mouse model of elastase-induced emphysema or in a mouse model of small airway remodeling due to chronic acrolein exposure." (PMID 34829671, 2021). "Importantly, elastase-induced airspace enlargement in this model was significantly worsened in Duox1–/– mice, suggesting that the absence of DUOX1 increases susceptibility to elastase-induced emphysema." (PMID 33301419, 2021). "To further explore a potential role for DUOX1 suppression in the development of COPD, we examined emphysema development in response to airway instillation of porcine pancreatic elastase (PPE), in age-matched WT and Duox1–/– C57BL/6NJ mice." (PMID 33301419, 2021). "However, we did not observe significant changes between WT and Duox1–/– mice with respect to overall neutrophil content during PPE-induced emphysema, based on intracellular MPO analysis, or with respect to induction of Cxcl1 mRNA." (PMID 33301419, 2021).